ESR1 (estrogen receptor 1)
Diseases named in the same sentence as ESR1 in open-access papers (continued):
Sharing a sentence is not in itself a finding about the gene and the disease.
tumor (continued). "Furthermore, many TFs, such as FOXA1 and ESR1, have been shown to contribute oncogenic activity in some cancer types, while acting as tumour suppressors in other contexts, often involving different protein–protein interactions." (PMID 33850167, 2021). "Finally, according to tumor malignancy, triple-negative cancer subtypes had higher ESR1 methylation levels than luminal/HER2+ or luminal A subtypes." (PMID 34863151, 2021). "Our results illustrated that ESR1 may act as a tumor suppressor by inhibiting the JAK/STAT3 signaling pathway." (PMID 33865377, 2021). "Another study has shown that in MBC ESR1 mutations were absent in primary tumor tissue samples and were detected only in metastases obtained after CTC characterization." (PMID 33799422, 2021). "However, Esr1 KO animals in our tumor study had reduced body weight, which we attribute to HCC-associated pathology." (PMID 34068249, 2021). "We also studied the expression of the estrogen receptor ESR1, in order to determine if tumor growth could be driven by a persistent ESR1 expression." (PMID 34771750, 2021). "In conclusion, our research revealed that ESR1 plays a critical role as a tumor suppressor in iCCA." (PMID 33865377, 2021). "Mutation types found within the ESR1 gene were missense in four tumors (D538G in No. 7 and No. 8, G442R in No. 14, and E380Q in No. 21), in-frame deletion in one tumor (G415_C417del in No. 9), and amplification in one tumor (No. 3)." (PMID 33854152, 2021). "The anticancer effects of AA on HCC were predicted to be associated with regulating tumor cell proliferation, apoptosis, angiogenesis, tumor invasion, and metastasis via various pathways such as EGFR signaling pathway, ESR1 signaling pathway, and CCND1 signaling pathway." (PMID 33688369, 2021). "Interestingly, mutations in estrogen receptor 1 (ESR1), the gene that encodes ERα, specifically the mutations Y537S, Y537N, Y537C, D538G, and E380Q, have been found in circulating tumor DNA and biopsies of metastatic BC with resistance to ET." (PMID 36046115, 2021). "Our research determined that ESR1 plays a critical tumor suppressor role in iCCA." (PMID 33865377, 2021). "Another patient acquired an ESR1 mutation, which was not detectable in the tumor or the first four plasma samples." (PMID 34298704, 2021). "However, under pathological conditions, ESR1, ESR2, and PGR have been demonstrated to be associated with tumorigenesis and tumor progression." (PMID 34322374, 2021). "Across available data, concordance rates appear to be lower when the ESR1 mutation status on ctDNA is compared with sequencing results obtained from archival tumor tissue samples rather than recent tumor biopsies, as performed in our study." (PMID 33777770, 2021). "We present the development and analytical validation of a highly sensitive and specific NAPA assay for the detection of four ESR1 mutations (Y537S, Y537C, Y537N and D538G) and its preliminary application in FFPE tumour tissues, CTCs, and paired plasma ctDNA of ER+ BrCa patients." (PMID 33535614, 2021). "According to the results presented, ESR1 mutations were present in the single CTCs and cfDNA, but not in the corresponding primary tumour tissues." (PMID 33535614, 2021). "Two of these three patients with ESR1 mutation detected on ctDNA and not on tumor tissue had a high disease burden, with more than three metastatic sites and visceral involvement." (PMID 33777770, 2021). "Additionally, DRFS from tested local recurrence as well as from primary tumor was also significantly shorter in the AF > 1% ESR1 mutant-positive patients (log rank p value = 0.017 and 0.011, respectively)." (PMID 32014063, 2020).
tumor (continued). "Analysis of ctDNA or tumor mRNA from patients enrolled in the PALOMA-3, NeoPalAna and MONALEESA-3 trials have identified Rb mutations, activating mutations in PIK3CA and ESR1, increased cyclin E1 and activation of the PDK1-AKT axis as some of the drivers of resistance." (PMID 32344635, 2020). "Resistance to endocrine therapies is complicated process that involves epigenetic alterations in the ESR1 gene, alternative splicing events, post-translational alterations and altered recruitment of co-regulators of ER; it also affects the tumor milieu and several other mechanisms." (PMID 32759784, 2020). "It is noteworthy that none of the three patients who had tumor tissue collected for molecular analysis at recurrence showed ESR1 mutations which have been associated with resistance to aromatase inhibitors in ER+ metastatic breast cancer." (PMID 32456205, 2020). "At the same time, YFJP was also found to enhance tumor-suppressive genes ESR1 and CASP3." (PMID 33292207, 2020). "ESR1 is up-regulated in tumor cells as well in the tumor microenvironment." (PMID 32041153, 2020). "RNAseq data taken from a TCGA study of 128 patients with primary LSCC showed that patients with higher than median tumor ESR1 expression (ESR1 > 5.56) had significantly higher survival rates as compared to patients with lower tumor ESR1 expression with p-value < 0.0001 and a hazard ratio of 0.02845." (PMID 32144339, 2020). "Indeed, mutations in ESR1, ERBB2 and NF1 were significantly enriched in ER+/HER2− tumours post hormone treatment compared to tumours from ER+/HER2− untreated patients." (PMID 32244556, 2020). "Moreover, we found that the expression of ESR1 and ESR2 were associated with clinical variables such as gender, age, race, grade, stage, and tumor status." (PMID 32536040, 2020). "We found that relative E2 amount was associated with ESR2 (ERβ) mRNA, but not that of ESR1 (ERα) in women with ER+/PR+ tumor." (PMID 31853538, 2020). "Because of increasing evidence that specific somatic tumor mutations are both prognostic (e.g. ESR1) and predictive in MBC (e.g. ESR1 and PIK3CA), somatic genomic testing has become standard of care and offers great promise in the advancement of novel therapeutics and precision cancer medicine." (PMID 32375690, 2020). "One consequence could be that PGRMC1 promotes tumor progression by upregulation of ERα protein and ESR1 mRNA directly via a transcriptional mechanism or indirectly via elevated steroid synthesis." (PMID 32660617, 2020). "The presence of ESR1 mutations in baseline tumours was significantly associated with lack of clinical benefit." (PMID 32641355, 2020). "Overall, the constitutive and E2-dependent growth of WT and ESR1 mutant expressing clones were approximately two-fold higher in monoculture than in the more complex models, consistent with the known suppression of tumor growth by relatively naïve cellular microenvironments." (PMID 31171849, 2019). "No activating mutations in ESR1 (exon 8 (c.1607-1621)) were observed in either single CTCs, CTCs clusters (isolated by DEPArray after ScreenCell® Cyto device enrichment) or primary tumour of that patient." (PMID 30691008, 2019). "The relative gene expression of ESR1 (mRNA for ER) was plotted for each tumour (y-axis)." (PMID 31174485, 2019). "The expression level was ESR1 4700 in tumor tissues and 1500 in normal tissues." (PMID 31182966, 2019). "It is notable that the post-AI ESR1-mutated tumour with the lowest oestrogen-regulated expression carried an E380Q mutation and was also HER2-positive though this is the only ESR1-mutated sample with HER2 overexpression making the importance of its association with low ERG expression uncertain." (PMID 30563991, 2019). "We also observed 20 mutations in the ESR1 gene in the IDC subtype in the GENIE dataset that were not identified in the same tumor subtype in TCGA." (PMID 30728399, 2019).
tumor (continued). "Thus, three of the four identified tumor subpopulations harbored four different resistance alleles, with the HER2 mutations displaying prompt response to neratinib, while the ESR1 mutations appeared to decline more modestly following fulvestrant." (PMID 31341951, 2019). "ESR1-Y537S and ESR1-D538G are partially sensitive to fulvestrant, and newer oral SERDs that have better bioavailability compared to fulvestrant, such as AZD9496, have shown promising results in treating tumor growth driven by ESR1 LBD point mutants in experimental models." (PMID 31106278, 2019). "A second possibility could be that CTCs reflect a transition of the tumour to increased aggressiveness and drug resistance in the HR+/HER2- subtype; for example, by the development of endocrine resistance with ESR1 mutations." (PMID 31553731, 2019). "High baseline ESR1 expression associated with better AI response in HER2+ tumours but not HER2− tumours." (PMID 31892336, 2019). "However, methylation at upstream alternative Esr1 promoters is tissue-specific, consistent with work demonstrating that Esr1 is expressed from these alternate promoters in distinct tissues and tumor types." (PMID 31181654, 2019). "The tumours fall into the three expected groups: MA tumours (AR high and ESR1 low) in the upper left quadrant, basal-like tumours (AR low and ESR1 low) in the lower left quadrant and luminal tumours (AR high and ESR1 high) in the upper right quadrant." (PMID 30899086, 2019). "In PAM50 analyses, tumours with a gene expression profile typical of luminal epithelial cells belong to the luminal subtype (of which there are two sub-categories), and are usually hormone receptor positive (ESR1+ PGR+)." (PMID 30248920, 2018). "This suggests the possibility of tumor suppressor activity for ESR1 in CRC." (PMID 29568567, 2018). "Furthermore, we found that endogenous E2 also promotes tumour growth through ESR1 in this model; ESR1 inactivation prolonged median survival by 20% even in mice not treated with hormones (p = 0.0003)." (PMID 29973689, 2018). "Likewise, analysing all predicted miRNA-oncogene interactions among the 231 COSMIC oncogenes, there were only 2 showing significant anticorrelation across tumour types with their predicted target miRNA (ESR1 and ABL2)." (PMID 30531873, 2018). "However, there was a significant upregulation of ESR1 (ERα) mRNA in OC samples from patients who had T3 tumours in comparison to OC samples from patients who had T1 tumours (p = 0.02)." (PMID 29390981, 2018). "ESR1 mutations are characterized by a frequency of no more than 2% in primary tumour compared to 30% in metastatic tissues among AI-resistant patients." (PMID 29769099, 2018). "Based on our results, we can hypothesize that TH and MH may reduce E2 and ESR1 expression to inhibit tumour growth." (PMID 28479926, 2017). "Importantly, ESR2 expression was inversely correlated with CRC progression and dKO of Esr1 or Esr2 in ovariectomized ApcMin/+ resulted in increased rate of tumor formation." (PMID 29383180, 2017). "In another small cohort of HR-positive Japanese MBC patients, whole exon sequencing of the ESR1 gene using NGS did not identify E380Q ESR1 mutation in their recurrent tumor samples and plasma samples." (PMID 29166868, 2017). "Subsequent measurement of tumor biomarker mRNA expression to detect conversion revealed significant decreases in ESR1 and PGR mRNA and MKI67 upregulation (all p < 0.001) in MT compared to PT of all tumor subtypes and ERBB2 upregulation in MT from triple-negative PT patients (p = 0.023)." (PMID 28881657, 2017).
tumor (continued). "We used the nCounter expression assay (NanoString®) to measure the expression of EGFR, erb-B2 receptor tyrosine kinase 2 (ERBB2), ERBB3, ERBB4, and estrogen receptor 1 (ESR1) genes using mRNA extracted from paraffin-embedded tumor tissues from 203 patients diagnosed with TNBC." (PMID 26907936, 2016). "We found that ESR1 mutations showed a trend towards higher prevalence in patients with tumours classified as luminal A by PAM50 compared with luminal B (41.4 versus 31.8%), as well as in patients with tumours harbouring PIK3CA mutations (44.4%)." (PMID 27174596, 2016). "Circulating tumour DNA is one method to avoid sampling bias, as was illustrated in this case, in which biopsy of a liver lesion did not reveal any of the three ESR1 mutations that were detectable in plasma at the time." (PMID 28027312, 2016). "In contrast, six out of the 14 patients did not have ESR1 mutations in the tumor tissue, but did show increases in cfDNA ESR1 mutations." (PMID 27102299, 2016). "In localised CRC, mRNA-based CD3Z/CD8 profiling of tumour immune response may have stage, site and tissue-specific prognostic significance, along with ESR1 expression." (PMID 25970543, 2015). "Thus, Esr1 expression and estrogen-dependent growth appear uncoupled in virus-based PyMT tumor models." (PMID 26429062, 2015). "The second patient had metastatic breast cancer and sequencing identified an ESR1 mutation in the cfDNA and metastatic site, but not in the primary tumor." (PMID 26317216, 2015). "However, during migration to the contra-lateral breast, a new deletion was established in the TN tumor at the ESR1 locus, either from subclone expansion or from a de novo mutation, and this rendered ER expression undetectable." (PMID 26554380, 2015). "Moreover, we correlated PELP1 with the ER mRNA expression (ESR1) and estrogen levels in plasma, normal breast tissue and tumor tissue." (PMID 26247365, 2015). "That ESR1 can have tumor suppressor activity is supported by various studies." (PMID 24464994, 2014). "The strong positive correlation between ESR1 gene expression and motif activity in both this study and the tumor study supports a negative interaction between the β-catenin signaling pathway and ESR1 in liver, potentially through direct repression of target gene by β-catenin." (PMID 24464994, 2014). "In addition, we will explore tumor markers, such as ESR1, and use more samples to validate and identify prognostic factors." (PMID 25188383, 2014). "A previous study has evidenced a differential expression pattern of the classical ERs in human normal and neoplastic Leydig cells with the exclusive presence of ESR1 in tumor cells, which could amplify estrogen signaling and could contribute to tumor growth." (PMID 24639669, 2014). "Further supporting this direct link between β-catenin and ESR1 repression is the fact that the highest correlations between ESR1 activity and mRNA expression levels are observed in the β-catenin KO and tumor studies, i.e. precisely those experiments where β-catenin activity is predicted to change." (PMID 24464994, 2014). "The absence of CXCR4 methylation was associated with the tumor stage, size, histological grade, lymph node status, ESR1 methylation and CXCL12 methylation, metastasis and patient death." (PMID 22220212, 2011). "Tumor subtypes are primarily categorized by expression of three cellular receptors: estrogen receptor (ER, HGNC gene symbol ESR1), progesterone receptor (PR, HGNC gene symbol PGR), and the epidermal growth factor receptor family member Her2/Neu (HGNC gene symbol ERBB2)." (PMID 21510869, 2011).
tumor (continued). "The most prominent tumor group was related to estrogen receptor(ESR1) expression." (PMID 17428335, 2007). "Another strategy is to treat emergent ESR1 mutation before clinical progression with a SERD, as seen in the PADA-1 trial, which assessed palbociclib plus ET, with a switch from an aromatase inhibitor to fulvestrant when ESR1 mutation was detected in circulating tumor DNA." (PMID 40427107, 2025). "In metastatic breast cancer, ctDNA assays can non-invasively determine tumor genetics such as PIK3CA and ESR1 mutation status, which direct the use of targeted therapies (PI3K inhibitors like alpelisib for PIK3CA-mutant tumors, or novel endocrine therapies for ESR1-mutant cases)." (PMID 40507825, 2025). "Among epithelial populations, we identified tumor cells (expressing Cd44, Ccnd1, Plau, Krt7), luminal alveolar (AV) cells (expressing Kit, Ehf, Csn3, Ltf), luminal hormone-sensing (HS) cells (expressing Prlr, Esr1, Pgr), and myoepithelial cells (expressing Myh11, Mylk, Myome1)." (PMID 41332581, 2025). "Subsequent studies demonstrated that in hormone-refractory prostate cancer, the reactivation of the ESR1 steroidal pathway could support tumor progression and invasiveness by enhancing the interaction between cancer cells and nerve cells, promoting both local invasion and metastasis." (PMID 40868045, 2025). "Our study assesses the prognostic value of PIK3CA and ESR1 mutations in DNA derived from extracellular vesicles (EV-DNA) in longitudinal plasma from 59 HR+/HER2-mBC patients previously exposed to aromatase inhibitors, with a comparative analysis against circulating tumor DNA (ctDNA)." (PMID 39684756, 2024). "Together, our results suggest that under hypoxic tumor conditions, abundant proangiogenic factors are released, highlighting VEGFA, which generates 2 different angiogenic phenotypes in male and female GBM patients, linked to sex hormone signaling, especially the expression of ESR1." (PMID 38411438, 2024). "Mutation of F404 would likely reduce ESR1 activity in the absence of other ESR1 mutations, which may have a deleterious effect on tumor growth, explaining the lack of F404 mutations observed without prior acquisition of an activating ESR1 mutation." (PMID 37982575, 2024). "ESR1 mutations have been detected in circulating DNA, while there was no mutation detected in the available tumor biopsy, indicating the presence of nonbiopsied tumor sites with mutations." (PMID 39272884, 2024). "Notably, the patients with ESR1 mutations in their primary tumor tissue (n = 3) had not received prior AI, one had received tamoxifen, and none had received hormone replacement therapy." (PMID 37511178, 2023). "In addition, analysis of circulating tumor DNA in the ESR1-mutant population showed a consistent reduction in ESR1 variant allele frequency at the 30 mg dose, which was not enhanced at higher doses." (PMID 38019116, 2023). "CB-103/fulvestrant combination treatment in vivo caused tumor regression and was superior to either agent alone in an ESR1-Y537S mutant model, while CB103 monotherapy or the doublet combination had comparable efficacy to fulvestrant alone in an ESR1 wild-type model." (PMID 37568775, 2023). "In conclusion, ESR1 amplifications and MAP3K mutations are novel genomic alterations that are selected upon adjuvant ETs in patients with advanced HR+ HER2- BC, and which represent promising targets of pharmacologic inhibition to reverse acquired tumor resistance." (PMID 36595552, 2023). "However, ESR1 drives tumor cell growth and proliferation, and its upregulation or the appearance of activating mutations may be responsible for resistance to hormonal treatments." (PMID 36831647, 2023).